TNF (tumor necrosis factor)
Diseases named in the same sentence as TNF in open-access papers (continued):
Sharing a sentence is not in itself a finding about the gene and the disease.
Obesity (continued). "In obesity, leptin levels are elevated and act as pro-inflammatory adipokines, inducing certain cytokines such as tumor necrosis factor-alpha (TNF-α), interleukin (IL)-1, and IL-6." (PMID 38255203, 2024). "In contrast, in WAT dysfunction in obesity, pro-atherogenic factors, such as FFAs, TNF-α, IL-6, resistin, and leptin, are secreted, which increase the development of atherosclerosis, internal plaque inflammation, and plaque vulnerability." (PMID 38051471, 2024). "In AT of people with obesity, the secretion of cytokines such as TNF-α and IL-6 is upregulated, which stimulates the hepatic release of acute-phase proteins such as C-reactive protein (CRP)." (PMID 38474344, 2024). "Mice fed the fatty acid ester of palmitic and hydroxystearic acids (PAHSA) showed decreased TNF-α and IL-1β expression in macrophages when fed a high-fat diet and PAHSA were linked with obesity-related inflammation." (PMID 39335332, 2024). "Subsequent studies in the JCI by the same group showed that TNF-α impairs the tyrosine kinase activity of the insulin receptor and that humans with obesity and insulin-resistant humans display elevated expression of adipose TNF-α." (PMID 39225103, 2024). "Hyper-glycolytic monocytes of people with obesity showed a normal IL-1ß, IL-6, and TNF response, whereas the IL-8 secretion in response to LPS was increased compared to monocytes of lean people." (PMID 39050851, 2024). "In consistent with obtained results regarding reduction of pre-inflammatory changes in obesity, suppressing an decreasing of TNF-α and IL-6 production in adipose tissue or serum, reducing IL-β1." (PMID 38504163, 2024). "In mouse adipose tissue, nesfatin-1 expression and secretion increase with diet-induced obesity and are influenced by pro-inflammatory cytokines (IL-6, TNF-α) and insulin." (PMID 39455994, 2024). "The highest levels were reported in obese subjects with metabolic syndrome, suggesting that TNF-α plays an important role in the progression of metabolic abnormalities related to obesity." (PMID 39149648, 2024). "High levels of adipokines, inflammatory modulators in obesity, are responsible for the secretion of pro-inflammatory cytokines, such as IFNγ, TNFα, IL-1β, IL-6, and IL-12." (PMID 39519568, 2024). "M1-macrophages release high levels of TNF-α in obesity which, in turn, provide an inflammatory stimulus that increases the production of IL-6, leptin and plasminogen activator inhibitor-1 (PAI-1)." (PMID 38133765, 2024). "TNF, a proinflammatory cytokine upregulated in obesity and AF, has been proven to increase the vulnerability to AF and atrial remodeling in animal models." (PMID 38156451, 2024). "It was assumed that the source of TNF-α and other cytokines in obesity was the adipocyte itself, but it was noted that pure cultures of adipocytes in vitro do not express TNF-α." (PMID 39225103, 2024). "In obesity, elevated levels of IL-6 and TNF-α and reduced levels of adiponectin are observed, and the associated chronic inflammation favors the development of cardiometabolic diseases." (PMID 37375693, 2023). "Animal models with diet-induced obesity have high levels of pro-inflammatory cytokines such as TNF-α, IL-1β, and IL-6 and activation of microglia and astrocytes in the hypothalamus." (PMID 37373230, 2023). "This suggests a strong association between CAV1 and different proinflammatory cytokines in obesity-mediated inflammation, particularly with TNF-α as an independent predictor." (PMID 37048092, 2023). "Many of the common secreted upstream regulators we identified, such as TNF, IL-1β, IFN-γ, IL-18, CD40L, IL-6, EGF, TGFβ, and IL-21, were previously reported to be associated with obesity and metabolic dysfunction." (PMID 36880999, 2023). "A similar trend in TNF-α expression was observed in primary human monocytes derived from healthy lean persons as well as those with overweight or obesity." (PMID 37894865, 2023).
Obesity (continued). "In pathological states such as obesity and metabolic excess, adipocytes often recruit more proinflammatory macrophages and other immune cells, and cytokines (such as TNF and IL-1) will significantly elevate to inhibit excessive adipogenesis." (PMID 36741233, 2023). "Our results have confirmed that patients with asthma and obesity have increased levels of circulating inflammatory cytokines such as TNF-α, IL-2, IL-4, and IL-17a despite the basic anti-inflammatory therapy." (PMID 37367676, 2023). "Treatment of miR-17–92−/− mice with anti-TNFα suppresses obesity and increases IL-10 via upregulation of Fos Proto-Oncogene expression, suggesting that miR-17–92 controls obesity by upregulating Il10 and suppressing Tnfa." (PMID 36994095, 2023). "Obesity induces a chronic low-grade inflammatory state, as does inflammaging, defined as age-related increases in pro-inflammatory cytokines, including TNF-α, IL-1β, and IL-6." (PMID 37681878, 2023). "This work investigated TPDM6315 extracts for their anti-inflammatory properties in LPS-stimulated RAW264.7 macrophages and TNF-α-stimulated 3T3-L1 adipocytes, as well as the potential anti-obesity activities in normal 3T3-L1 adipocytes." (PMID 37367060, 2023). "The increased risk of postoperative infection is a crucial complication to consider in patients with obesity, owing to the frequent use of immunosuppressive agents, particularly TNF- α inhibitors." (PMID 38137477, 2023). "Both diseases are related to obesity via the complex influence of proinflammatory cytokines (IL-6, IL-17, TNF-α) and adipokines, leading to cardiometabolic disturbances." (PMID 37891954, 2023). "In individuals with obesity, the macrophage-infiltrated visceral fat becomes a major source of TNFα production." (PMID 37755259, 2023). "Pro-inflammatory cytokines such as TNF-α, IL-1β, and IL-6, which are mainly produced by immune cells and adipocytes, play a vital role in the pathogenesis of obesity and OA." (PMID 37703108, 2023). "In the case of obesity, the amount of proinflammatory cytokines tumor necrosis factor alpha, interleukin 1, and interleukin 6 produced from adipocytes increases." (PMID 37909201, 2023). "Serum TNF-α levels increase with inflammation, septic shock, rheumatoid arthritis, host parasitic diseases, obesity, and developing insulin resistance." (PMID 37763806, 2023). "Chronic inflammation and elevated TNFα levels in individuals with obesity and leptin resistance contribute to hyperleptinemia." (PMID 37755259, 2023). "TNF-α and TNF signaling are hallmarks of inflammation and have been related to the cardiovascular pathophysiology of atherosclerosis, sepsis, diabetes, and obesity, among others." (PMID 37299535, 2023). "Another among these genes is TNF alpha, which is involved in inflammatory processes connected to resistance to insulin, obesity, dyslipidemia and cardiovascular disease." (PMID 38248733, 2023). "In a randomized, double-blind, placebo-controlled clinical study, the multi-strain probiotic Ecologic® Barrier influenced TNF-α and IL-6 in a dose-dependent manner in postmenopausal women with obesity." (PMID 37371961, 2023). "For instance, circulating levels of chemerin strongly correlated with markers of inflammation, such as TNF-α, IL-6, and C-reactive protein, in the context of obesity." (PMID 36883565, 2023). "Obesity is characterized by chronic low-grade inflammation, mainly mediated by adipose tissue-derived cytokines such as TNF-α and IL-6." (PMID 37834153, 2023). "It would appear that there is a direct link between obesity-related insulin resistance and the adipose tissue expression of tumour necrosis factor (TNF-α)." (PMID 37107955, 2023). "IL-1β, TNF-α and IL-6 are inflammatory cytokines correlated with and involved in obesity-related inflammation and insulin resistance, respectively." (PMID 37796781, 2023).
Obesity (continued). "In this study, a higher risk of obesity was found in older participants (≥ 40 years) with the “AA” genotypes of APOB SNP rs512535 (Pinteraction = 0.004) and tumor necrosis factor (TNFA) SNP rs361525 (Pinteraction = 0.007) with low levels of ME." (PMID 36776603, 2023). "They firstly recognized that patients suffering from obesity, presented 2.5-fold higher TNF-α mRNA levels than controls with normal weight." (PMID 37239098, 2023). "Th cell transcriptome analysis identified upregulation of genes in the cytokinesis cycle 42 pathway (associated with TNF-α and IFN-γ expression) in Th cells of children with obesity-related asthma." (PMID 37377958, 2023). "WAT-released pro-inflammatory mediators, such as FFAs and TNFα, play a critical role in inducing myocyte inflammation and dysfunction, in obesity." (PMID 36829858, 2023). "Serum from DIO-LFD mice had a similar overall suppression of obesity-driven elevation of adipokines except glucagon and TNF-α." (PMID 37698918, 2023). "The innate immune system is activated in obesity; M1-polarized macrophages that display a pro-inflammatory phenotype and secrete cytokines such as TNF-α are increased during obesity." (PMID 36982743, 2023). "It was this important observation that proinflammatory TNF-α was highly expressed within adipose tissue in several rodent models of obesity and, when TNF-α was neutralised, insulin action was enhanced." (PMID 37627482, 2023). "Treatment with 17β-estradiol, leptin, IL-6, and TNF-α (ELIT) for obesity-related inflammation also decrease mitochondrial function and increase oxidative stress, aggressiveness, and motility in cell lines with low estrogen receptor beta (ERβ) expression." (PMID 36880535, 2023). "Obesity with visceral fat accumulation, which increases the levels of leptin, TNFα, IL-6 and resistin, and decreases the level of adiponectin, is related to cancer risk and mortality." (PMID 36879265, 2023). "Obesity exerts a multitude of effects both locally and systematically, through a series of inflammatory mediators (increased leptin, reduced adiponectin, TNF-α, IL-6), growth factors (insulin, IGF-1), and metabolism molecules (visfatin, grehlin, and resistin)." (PMID 37834153, 2023). "Elevated levels of TNF-α have been found in depression and manic states, bipolar disorder, and obesity." (PMID 37049434, 2023). "Specifically, in obesity, dysfunctional adipose tissue predominantly secretes proinflammatory adipokines (e.g., leptin, resistin, interleukin-6 (IL-6), and tumor necrosis factor-α (TNF-α)) in detriment of the anti-inflammatory ones (e.g., adiponectin)." (PMID 37432255, 2023). "Insulin resistance in obesity elevates oxidative stress and inflammatory cytokines, such as TNF-α and IL-6 in endothelial cells, which decreases nitric oxide bioavailability and induces endothelial dysfunction." (PMID 37790032, 2023). "In subjects with obesity, adiponectin plasma levels are usually low and proinflammatory cytokines, such as leptin, resistin, IL-6, IL-10 and tumor necrosis factor (TNF-α) are usually elevated, thus producing a pro-inflammatory metabolic pattern." (PMID 37630854, 2023). "Another study found that TNF‐α can inhibit insulin action and play an important role in obesity‐derived insulin resistance." (PMID 37003602, 2023). "Some data derived from animal models indicate that TNF-α contributes to the etiology of some obesity-related conditions, including insulin resistance." (PMID 37730940, 2023). "Given that no other studies have examined the associations of other inflammatory markers with quality of life in metabolically unhealthy people with obesity, our findings regarding IL-6 and TNF-α can be considered of significant importance." (PMID 37529617, 2023). "PUE can also significantly reduce TNF-α levels in obese mice to reduce obesity-induced inflammation and dyslipidemia." (PMID 37755746, 2023).
Obesity (continued). "The elevation of tumor necrosis factor (TNF-α) in adipose tissue of individuals with obesity has been substantiated." (PMID 38045856, 2023). "In the diet-induced obesity mice model, the purple corn cob extract treatment upregulated the M2 markers (ArgI, Fizz1, and TGFβ) and downregulated the inflammatory mediators (TNF-α, IL-6, IL-1β, and COX-2) by suppressing NF-kB signaling." (PMID 38005786, 2023). "ER stress and inflammation in obesity result in the elevation of pro-inflammatory cytokines, including IL-6 and TNF-α." (PMID 38140341, 2023). "It is clear that tumor necrosis factor-α (TNF-α) and various other inflammatory mediators are overexpressed in adipose tissue in experimental mouse models of obesity and humans." (PMID 36769289, 2023). "Other studies carried out on diet-induced obese mice demonstrated that a BC fruit extract reduced obesity-induced inflammation in adipose tissue and splenocytes by lowering TNF-α transcription." (PMID 37110805, 2023). "IL-10 has also been found to suppress the production of pro-inflammatory cytokines and protect from TNFα-induced insulin resistance in obesity." (PMID 36994095, 2023). "Obesity predisposes to a chronic inflammatory state which is accompanied by higher levels of pro-inflammatory cytokines such as RANTES, TNF-α, IL-6 and IL-18." (PMID 36771387, 2023). "One proposed mechanism underlying the link between obesity, inflammation, and CRC risk is through the secretion of inflammatory cytokines such as TNF-α, IL-1β, IL-6, and monocyte chemoattractant protein (MCP)-1 by adipose tissue-derived cells." (PMID 36839339, 2023). "In individuals with obesity, proinflammatory cytokines, such as TNF-α and IFN-γ produced by adipose tissue interfere with tight junctions of the intestinal barrier, promoting increased permeability." (PMID 36831188, 2023). "Regarding its potential metabolic role mediating obesity and IR, TNF-α was found to be increased in rodent obesity, whereas neutralization of TNF-α in animals with obesity and IR resulted in higher IS." (PMID 37239098, 2023). "Adipocytes and macrophages in adipose tissue can produce various proinflammatory cytokines, and elevated concentrations of IL-6 and TNF-α are increased in adipose tissue and serum during obesity." (PMID 36982669, 2023). "In individuals with obesity, inflammatory markers such as IL-6, CRP, and TNF-α have been associated with the progression of discogenic back pain." (PMID 37959372, 2023). "In the spleen, in the case of TNFα, there was only a significant effect of obesity (F = 19.43; p = 0.0023)." (PMID 37892420, 2023). "One of the components of the pathogenesis of obesity is inflammation, and many inflammatory cytokines such as C-reactive protein, IL-6, and TNF-α play a vital role in the disease and are also commonly raised in seborrheic dermatitis patients." (PMID 37503468, 2023). "It is generally accepted that the serum level of TNF-α is mildly increased in people affected by obesity." (PMID 36765351, 2023). "Progranulin is also recognized as an adipokine and, together with TNF-α and GDF-15, is known to be associated with obesity." (PMID 37371414, 2023). "In the study of obesity and chronic inflammation, some scholars used TNF-α, CRP, and hs-CRP to evaluate chronic inflammation." (PMID 37582770, 2023). "Further evidence supports the role of obesity-induced inflammatory responses (IL-6, TNF-α, and leptin) in tamoxifen-acquired BC resistance." (PMID 36880535, 2023). "Due to its pro-inflammatory nature, manifested by the activation of TNF-α, interleukins, and promotion of oxidative stress, resistin is considered to be involved in pathologies such as obesity, insulin resistance, neoplasia, and atherosclerosis." (PMID 37233709, 2023). "Obesity also contributes to the second hit as adipose tissue releases inflammatory mediators such as leptin, tumor necrosis factor (TNF)-alpha, and interleukin (IL)-6, which damage hepatocytes." (PMID 36834895, 2023).
Obesity (continued). "It has been shown that the inflamed adipose tissue of obese individuals releases a variety of cytokines, such as IL-18, IL-6, IL-1, and TNF-α, thereby contributing to obesity-induced insulin resistance." (PMID 37876013, 2023). "The finding that patients with SO have higher levels of TNF-α in circulation than those with concurrent obesity or sarcopenia is consistent with the potential mechanism in the present and previous studies." (PMID 37853348, 2023). "Particularly, tumor necrosis factor-a (TNF-a), whose expression has been demonstrated to be increased in human obesity, contributes to generate IR by inhibiting tyrosine kinase activity at the insulin receptor." (PMID 36675276, 2023). "It has been suggested that individuals with an elevated BMI, particularly those with obesity, have elevated concentrations of serum inflammatory markers, such as C-reactive protein, tumour necrosis factor alpha (TNF-α), and interleukin 6 (IL-6)." (PMID 38097936, 2023). "Obesity can lead to insulin resistance and affect insulin secretion and utilization As obesity progresses, fatty tissue begins to secrete hormones such as tumor necrosis factor-alpha (TNF-α) and interleukin-6 (IL-6), which exacerbate insulin resistance." (PMID 37740187, 2023). "In the context of obesity and MS, TNF-α is secreted by macrophages from the stromal vascular tissue associated with adipose tissue." (PMID 36788619, 2023). "It is known that TNF-α expression in obesity plays a key role in induction of chronic low-grade inflammation and insulin resistance." (PMID 37894865, 2023). "The interplay between CAV1 and the TNF-α signaling pathway is intriguing and has potential as a target for therapeutic interventions in obesity and metabolic syndromes." (PMID 37048092, 2023). "Adipocytokines, such as tumor necrosis factor α (TNF-α) or interleukin (IL)-6, are generally elevated with increasing adiposity and play an important role in the development of metabolic complications in obesity." (PMID 36674952, 2023). "Proinflammatory cytokines TNFα, IL-1β, and IL-6, are produced by macrophages and adipocytes, the primary cells involved in obesity and metabolic disorders." (PMID 36830566, 2023). "The fact that psoriatic patients dealing with obesity were characterized by worse response to biological agents, including tumor necrosis factor inhibitors, is also a significant result which should be further examined." (PMID 38202116, 2023). "Obesity causally increases gastric cancer, likely mediated by persistent AKT1/IL-6/TNF upregulation." (PMID 37954072, 2023). "Obesity increases pro-inflammatory IL-6 and TNF-α levels and decreases anti-inflammatory hormone adiponectin." (PMID 37229273, 2023). "Very recently it has also been shown that humans with obesity have a higher expression of vascular/perivascular TNF-α, in addition to NF-Κb and IL-6." (PMID 37109222, 2023). "Rats with obesity and arthritis presented an increase in paw inflammation, in the level of plasma tumor necrosis factor-α (TNF- α), dyslipidemia, and oxidative stress." (PMID 38138560, 2023). "TNF influences obesity-related IR because this cytokine inhibits insulin receptor tyrosine kinase phosphorylation." (PMID 36677054, 2023). "The administration of HRCHFC diet for 8 weeks initiated the development of obesity and low-grade chronic inflammation mediated by the liberation of pro-inflammatory cytokines like IL-6 and TNF-α." (PMID 37033655, 2023). "Obesity is characterized by mild chronic inflammation, which leads to the release of proinflammatory cytokines such as interleukin-6 and tumor necrosis factor-α." (PMID 37397759, 2023). "Recently, several studies have shown that proinflammatory cytokines such as interleukin (IL)-1β, IL-6, and tumor necrosis factor-α (TNF-α) in adipocytes and macrophages contribute to the onset and progression of obesity." (PMID 37570719, 2023).